INS (insulin)
Diseases named in the same sentence as INS in open-access papers (continued):
Sharing a sentence is not in itself a finding about the gene and the disease.
Hypoglycemia (continued). "Their neonatal offspring consequently displayed disrupted glucose homeostasis, characterized by concurrent hypoglycemia, hyperinsulinemia, and enhanced insulin secretion." (PMID 41683286, 2026). "The insulin tolerance test (ITT) is traditionally considered the gold standard test for the dynamic evaluation of the HPA axis, assessing the SC response to insulin‐induced hypoglycaemia." (PMID 40874801, 2026). "Conversely, a small, but statistically significant, difference was seen in bsAUC for insulin on the hypoglycemia days, with insulin being slightly higher during placebo compared to GLP-2." (PMID 41541287, 2026). "This article reports a patient who took beraprost sodium, clopidogrel, atorvastatin calcium, and the PPI pantoprazole and was subsequently diagnosed with IAS, presenting with a high IAA level, refractory hypoglycemia, and markedly elevated insulin levels." (PMID 42318218, 2026). "In patients with CHI, the regulatory pathway between glucose and insulin secretion is impaired, leading to inadequate insulin secretion and consequently hypoglycemia." (PMID 40705962, 2026). "She responded well to B-lymphocyte depletive therapy (rituximab) with a fall in insulin antibody levels and returned to usual T1D management with a marked improvement in severity of hypoglycemia." (PMID 41472947, 2026). "As shown in previous studies among insulin-based treatment strategies, FRC is associated with a lower incidence of hypoglycemia and less weight gain compared to multiple daily injections, while achieving comparable glycemic control." (PMID 41268167, 2025). "Although multiple studies have confirmed insulin therapy, impaired renal function, and suboptimal glycemic control as significant predictors of hypoglycemia, reliably forecasting such events remains difficult." (PMID 41040859, 2025). "The highest proportion of patients who reported hypoglycemia were using insulin (n = 152, 41.75%), followed by those receiving sulfonylureas (n = 98, 26.92%), metformin (n = 69, 18.95%), and combination treatment (n = 45, 12.36%)." (PMID 40926927, 2025). "This necessitates meticulous glucose monitoring and co-administration of dextrose-containing fluids to prevent iatrogenic hypoglycemia during insulin therapy." (PMID 40585463, 2025). "Increased plasma glucagon leads to an increase in hepatic glucose production in situations of hypoglycemia, counteracting the hypoglycemic effects of insulin." (PMID 39549141, 2025). "In recent years, technological innovations such as insulin pump therapy and continuous glucose monitoring (CGM) systems have emerged to improve diabetes management, leading to a reduction in the risk of hypoglycemia, particularly severe hypoglycemia." (PMID 40871638, 2025). "In our center, He was admitted to the endocrinology ward and serum insulin, C‐peptide level, and urinary ketones were sent after inducing fasting hypoglycemia." (PMID 40124204, 2025). "Concurrently, pancreatic beta cells decrease insulin synthesis in response to hypoglycemia, which further reduces the cell uptake of glucose." (PMID 40005882, 2025). "This protocol significantly enhanced transplant outcomes and led to successful cases of insulin independence in brittle T1D patients, characterized by severe hypoglycemia and glycemic instability despite insulin therapy." (PMID 40124184, 2025). "Insulinomas are rare, functional pancreatic neuroendocrine tumors (PNETs) that originate from beta cells of the islets of Langerhans and are characterized by unregulated insulin secretion, leading to recurrent episodes of hypoglycemia." (PMID 40757084, 2025). "When considering side effects of insulin, the concerns which are most commonly reported are injection site reaction, hypoglycemia and weight gain." (PMID 40156735, 2025). "HH is a rare metabolic condition characterized by excessive insulin secretion, resulting in recurrent hypoglycemia." (PMID 40273002, 2025).
Hypoglycemia (continued). "Nonetheless, the insulin group had a greater rate of hypoglycemia and weight gain, which can influence the adherence to the medication long-term and the quality of life of the patients." (PMID 40959330, 2025). "The prolonged exposure of physiological levels of insulin under hypoglycaemia revealed non‐beneficial effects of low glucose." (PMID 39471069, 2025). "A census study from Scotland among diabetic insulin users revealed that around 10% encountered problems during travel, mainly hypoglycemia." (PMID 40901237, 2025). "Given the repeated history of hypoglycemia, the confirmation of Whipple's triad, and elevated fasting C-peptide and insulin levels, a diagnosis of insulinoma was strongly suspected." (PMID 39968426, 2025). "Misconceptions regarding insulin use, lipodystrophy prevention, hypoglycemia correction, and appropriate consumption of snacks and carbohydrates were effectively addressed." (PMID 40008736, 2025). "Typically, hypoglycemia is attributed to substance abuse (especially insulin use) and poor dietary management." (PMID 40469441, 2025). "Acute complications such as hypoglycemia and diabetic ketoacidosis are managed through fluid resuscitation, electrolyte correction, insulin infusion, and prompt glucose or glucagon administration." (PMID 40716044, 2025). "These responses reflect clinical challenges in T1DM management, where the balance between effective glycemic control and hypoglycemia prevention remains difficult to achieve, especially with rigid or less physiological insulin regimens." (PMID 41293743, 2025). "However, due to the insulin-sensitizing effects of DPP-4 inhibitors and the inherent risk of hypoglycemia associated with premixed insulin, we hypothesize that the combination of vildagliptin and premixed insulin may lead to an increased likelihood of hypoglycemic episodes." (PMID 40620795, 2025). "In general, we recommend keeping the MiniMed 780G system in automated mode during PA when a glucose decrease is expected, in addition to setting a Temp Target, and reducing prandial bolus insulin by 25–33% to minimise hypoglycaemia." (PMID 39653802, 2025). "Ultimately, long-term treatment of hypoglycemia due to insulin secretagogue and exogenous insulin primarily involves addressing the underlying problem by stopping the offending medication." (PMID 40648766, 2025). "A concern regarding the use of a GLP-1RA in patients with T1D in clinical practice would be the risk of hypoglycemia, as GLP-1RAs not only enhance endogenous insulin secretion but also suppress glucagon release, a major counter-regulatory hormone." (PMID 40760325, 2025). "Biochemistry tests during two spontaneous hypoglycemia episodes confirmed endogenous hyperinsulinemic hypoglycemia (low serum glucose levels, high serum insulin, and high serum C-peptide with a low β-hydroxybutyrate)." (PMID 40375949, 2025). "Based on the episodes of hypoglycemia, high levels of insulin, high-normal levels of C-peptide, and positive insulin autoantibodies, the patient was diagnosed with IAS." (PMID 39968421, 2025). "Secondary outcomes included change in time in range (TIR) from baseline to 6 months, change in time below range (TBR), change in nocturnal hypoglycemia, glucovariability, insulin dose and body weight." (PMID 41268167, 2025). "The DIAMOND study indicated that hypoglycemia events were more frequent in patients on sliding scale insulin therapy, suggested a strict monitoring of blood glucose levels." (PMID 40901501, 2025). "While once‐daily insulin demonstrated slightly superior HbA1c reduction, once‐weekly insulin presents potential advantages in patient adherence, balanced against increased risks of injection site reactions and nocturnal hypoglycemia." (PMID 40186384, 2025). "Insulin use was the strongest predictor of post-coital hypoglycemia, with nearly one-third of insulin users affected compared to only 3% of non-users." (PMID 41030722, 2025).
Hypoglycemia (continued). "For instance, long-acting insulin analogs such as glargine insulin and detemir insulin, which have fewer side effects on weight gain and nocturnal hypoglycemia, have gradually been replacing NPH insulin." (PMID 41171710, 2025). "Despite a gradual reduction in insulin doses, the persistence of hypoglycemia led to insulin cessation." (PMID 40290321, 2025). "Even with conventional intensive insulin therapy, frequent hypoglycemia (estimated at 5–15% of total blood glucose measurements) is often necessary to maintain the mean glycemic level within treatment targets (<150 mg/dL)." (PMID 40871638, 2025). "Difficulties in maintaining a balance in intensive insulin therapy and the fear of hypoglycemia are also mentioned as some of the reasons for weight gain." (PMID 40277935, 2025). "A major challenge in developing injectable hydrogels for insulin delivery is mitigating the initial burst release, which risks hypoglycemia and rapid insulin depletion." (PMID 40292663, 2025). "Based on these findings, it is recommended to gradually reduce insulin doses when initiating tirzepatide to prevent hypoglycemia and optimize glycemic control." (PMID 40746803, 2025). "Although severe or persistent hypoglycemia is frequently asymptomatic, it can be brought on by an inadequate glucose supply, excessive insulin production, metabolic demand, or malfunctioning counter-regulatory systems." (PMID 40953062, 2025). "To enhance the management of hypoglycemic events, we recommend frequent SMBG monitoring, particularly during the initial weeks of insulin titration, to detect and address hypoglycemia promptly." (PMID 39694849, 2025). "Studies monitoring the effect of a given insulin infusion rate were frequently correlated with duration of insulin infusion, hospital or intensive care length of stay, and complications such as hypoglycemia, hypokalemia and cerebral edema." (PMID 40407548, 2025). "A critical sample for hypoglycemia was drawn, including insulin, C-peptide, free fatty acids, growth hormone, cortisol, ammonia, lactate, beta-hydroxybutyrate, acylcarnitine profile, free and total carnitine, and urine organic acids." (PMID 41458770, 2025). "Postoperative hypoglycemia following pheochromocytoma resection results from a sudden drop in circulating catecholamines, which previously suppressed insulin secretion and promoted insulin resistance." (PMID 40649858, 2025). "A total of 24.2% of the patients had hypoglycemia, predominantly among insulin users; adverse effects were reported by 10.6% of patients, such as constipation, nausea, and diarrhea." (PMID 40842739, 2025). "Factors that would increase users’ trust in CC apps include transparency about safety mechanisms to prevent accidental overdosing of insulin or hypoglycemia (n=147, 75%) and endorsements based on validated clinical trial results (n=146, 74.5%)." (PMID 40153793, 2025). "Prolonged high income was also associated with better metabolic profile, reduced insulin use, lower prevalence of CKD, and fewer previous severe hypoglycemia events." (PMID 40455444, 2025). "Further studies employing dynamic hormonal tests, such as low-dose ACTH stimulation or insulin-induced hypoglycemia, are required to confirm the clinical relevance of latent AI in glucose regulation." (PMID 40932945, 2025). "Limiting high‐glycaemic‐index carbohydrates reduces the postprandial glucose spike and insulin response preceding hypoglycaemia." (PMID 39392055, 2025). "The high use of insulin aligns with its role in managing blood glucose levels in T2DM patients, but also highlights the associated risk of hypoglycemia." (PMID 41393767, 2025). "In one study, individuals on an LCD exhibited a blunted glycemic response to glucagon during insulin-induced hypoglycemia." (PMID 40573112, 2025). "estimated the economic cost of insulin-related hypoglycemia in Algerian adults with T1DM and T2DM at DZD 42.9 billion (USD 334 million), with T2DM accounting for 74%." (PMID 40303934, 2025).
Hypoglycemia (continued). "Most are benign and slow-growing, but their clinical significance stems from their inappropriate secretion of insulin, which leads to recurrent episodes of hypoglycemia." (PMID 40647278, 2025). "In an animal model, a single bout of prolonged exercise markedly attenuated counterregulatory responses to insulin‐induced hypoglycemia performed immediately afterwards." (PMID 40926369, 2025). "Intensive care admission was observed to improve insulin infusion duration and common complications such as hypoglycemia and readily measurable biochemistry such as serum bicarbonate, ketones, pH and lactate." (PMID 40407548, 2025). "In contrast, in insulin secretagogue-induced hypoglycemia, endogenous insulin production is ongoing, as evidenced by inappropriately non-suppressed or elevated c-peptide, pro-insulin, and insulin levels." (PMID 40648766, 2025). "In most clinical settings, simultaneous measurement of plasma insulin and C-peptide can establish the diagnosis of factitious hypoglycemia." (PMID 39030378, 2025). "Once endogenous insulin-mediated hypoglycemia is uncovered, localization with endoscopic ultrasound is the preferred imaging modality, due to its high sensitivity (81%) and specificity (90%)." (PMID 40648766, 2025). "This systematic review underscores the evolving landscape of DKA and hypoglycemia management, with evidence supporting the use of subcutaneous insulin, low-dose insulin infusions, and balanced crystalloids to improve outcomes and reduce complications." (PMID 41262789, 2025). "GTT involves ingestion of a glucose solution to evaluate how the body processes glucose, while ITT involves intravenous insulin administration to induce hypoglycemia, assessing the body's response to insulin and counter-regulatory hormone systems." (PMID 40015624, 2025). "Hypoglycemia-induced brain injury or hypoglycemic encephalopathy is often due to exogenous insulin use in diabetic patients, sepsis, alcoholism, drugs such as sulfonylureas, and hepatic, renal, and endocrine disorders." (PMID 40726866, 2025). "Congenital hyperinsulinism is a rare disorder characterized by hypoglycemia and inappropriately elevated insulin levels." (PMID 40605820, 2025). "Although peripheral insulin is crucial for lowering blood glucose levels, central insulin is also involved in the counterregulatory response to hypoglycemia." (PMID 39821966, 2025). "Prior to surgery, on i.v. glucose only, serum insulin values during hypoglycemia were within (n=4) or above (n=1) the normal range of 18–174 pmol/L confirming ongoing HH." (PMID 41561050, 2025). "It is diagnosed when there is increased insulin action and/or inadequate suppression of plasma insulin during spontaneous or fasting-induced hypoglycemia." (PMID 40828772, 2025). "Environmental factors other than light, including insulin-induced hypoglycemia, can override the inhibitory effects of light and accelerate melatonin synthesis." (PMID 40234702, 2025). "In these people the limitations of insulin therapy also mean that they are hypoglycaemia prone—again it is useful to know that is usual." (PMID 40035222, 2025). "As evident from the system responses, the proposed FRNN-FO algorithm accurately identifies the chaotic behavior of hypoglycemia in the insulin-glucose regulatory system, outperforming other models, particularly in the testing phase." (PMID 41345203, 2025). "In this case, the endocrinologist utilised Mixtard insulin, which is 70% intermediate-acting insulin, and titrated it downwards as blood glucose levels reduced and the patient exhibited signs of hypoglycaemia." (PMID 41567924, 2025). "While significant insulin dose reductions after the initiation of semaglutide or tirzepatide therapy are generally required to avoid hypoglycemia, excessive insulin dose reductions can lead to DKA or euDKA." (PMID 40004833, 2025).
Hypoglycemia (continued). "Because the protein also is a negative regulator of insulin secretion in pancreatic β-cells, inactivating mutations in the SCHAD gene (HADH) cause congenital hyperinsulinism of infancy (CHI) and severe hypoglycemia." (PMID 40474078, 2025). "Reward function optimization: the entropy-based reward function incorporated glucose stability, insulin efficiency, and hypoglycemia prevention." (PMID 40614090, 2025). "Studies have shown that among elderly patients in China using insulin or sulfonylureas, approximately 40% experience at least one mild hypoglycemic event annually, while 5%–10% encounter severe hypoglycemia." (PMID 41346986, 2025). "Sympathetic innervation of the islets plays a role in the glucagon response following insulin-induced hypoglycemia." (PMID 40940782, 2025). "Insulin and oral hypoglycemic medications are widely used to treat type‐2 DM even though they can result in hypoglycemia, weight gain, insulin allergy, and gastrointestinal problems." (PMID 40641385, 2025). "The observed hypoglycemia likely arises from the dual impact of increased glucose utilization to meet thermoregulatory demands and enhanced insulin absorption due to peripheral vasodilation." (PMID 40852430, 2025). "The metformin group had lower maternal GWG and GAB and a lower incidence of preterm birth than the insulin group, with a trend for neonatal hypoglycemia." (PMID 39860070, 2025). "By contrast, PRIMO-FRL explicitly optimizes multiple clinical goals, including hypoglycemia prevention, glucose stability, and insulin efficiency, making it better suited for real-world applications where trade-offs between multiple factors are necessary." (PMID 40614090, 2025). "These patients exhibit increased insulin sensitivity, which enhances glucose utilization and results in fasting hypoglycemia." (PMID 40475996, 2025). "When initiating SGLT2 inhibitors in patients already on insulin with HbA1c < 58 mmol/mol and eGFR > 45 mL/min/1.73 m2, consider reducing the insulin dose by 20% to avoid hypoglycemia." (PMID 40426903, 2025). "Injections do not control glucose levels automatically and it is hard to match insulin doses to food and activity, resulting in both high and low blood sugar levels (hypoglycaemia)." (PMID 40520684, 2025). "Engaging in high-intensity or prolonged physical activity presents unique glycemic challenges, including exercise-induced hypoglycemia and insulin adjustments in response to fluctuating energy demands." (PMID 40217942, 2025). "Subsequent insulin analogs, like the basal analogs glargine and detemir, improved absorption consistency and reduced nocturnal hypoglycemia." (PMID 39810242, 2025). "As soon as plasma glucose decreases to below 250 mg/dL, 5-10% dextrose should be used in addition to the normal saline to prevent hypoglycemia, while insulin is used to correct the ketonemia." (PMID 41141170, 2025). "The cornerstone of DCM treatment involves rigorous glycemic control, with insulin and other hypoglycemic agents mandating strict clinical supervision by physicians to prevent complications such as hypoglycemia." (PMID 40491718, 2025). "The clinical and biochemical data presented above suggested endogenous insulin-mediated hypoglycemia; therefore, P-NET was suspected and abdominal imaging investigations were performed." (PMID 39941267, 2025). "NEN can be diagnosed via imaging surveillance, and also, although less often, by symptoms related to hypergastrinemia or unregulated insulin secretion (hypoglycemia)." (PMID 39826015, 2025). "The program also addressed common misconceptions, including managing insulin types, preventing lipodystrophy, adequately correcting hypoglycemia, and incorporating sweets and other carbohydrate-rich foods into the diet when appropriate." (PMID 40008736, 2025). "The safety profile aligns with a US-based randomized controlled trial that showed similar hypoglycemia rates with automated insulin titration guidance compared to standard care." (PMID 39924297, 2025).